PRSS3 (serine protease 3)
Diseases named in the same sentence as PRSS3 in open-access papers (continued):
Sharing a sentence is not in itself a finding about the gene and the disease.
retinopathy (1 paper, 2024). "In GWAS analysis, we found 12 SNPs had a significant association (p < 10-4) with HCQ retinopathy in genes LCE4A, HRNR, OR2T4, NUDT17, CCDC66, PRSS3, PABPC1 and IGHV." (PMID 38548946, 2024).
PRSS3 also shares sentences with these, for which no sentence is quoted: celiac disease (5 papers); hepatocellular carcinoma (3); ovarian cancer (3); autoimmune disease (2); Autoimmunity (2); esophageal cancer (2); lung squamous cell carcinoma (2); -dependent (1); Barrett’s Metaplasia (1); bipolar disorder (1); chronic pancreatitis (1); colitis (1); colorectal cancer (1); COVID-19 (1); dementia (1); ductal carcinoma of the breast (1); esophageal squamous cell carcinoma (1); Hashimoto thyroiditis (1); Hypertension (1); inflammatory bowel disease (1); irritable bowel syndrome (1); liver cancer (1); lymph node metastasis (1); malaria (1); medulloblastoma (1); membranous nephropathy (1); metabolic disorders (1); neurodegenerative disease (1); non-small cell lung carcinoma (1); pancreatitis (1).
A further 3 diseases each share a sentence with PRSS3 in 1 paper.